CDH8 (cadherin 8)
Description:
Cadherins are calcium-dependent cell adhesion proteins. They preferentially interact with themselves in a homophilic manner in connecting cells; cadherins may thus contribute to the sorting of heterogeneous cell types.
Synonyms: Nbla04261
Tractability: Antibody: its Gene Ontology location is reachable by antibodies, with high confidence; UniProt places it where antibodies can reach, with medium confidence; UniProt predicts a signal peptide or a membrane-spanning region; the Human Protein Atlas places it where antibodies can reach. PROTAC: its protein half-life has been measured.
Gene: Protein-coding gene on chromosome 16 (61,647,242 to 62,037,035, reverse strand). Ensembl gene ENSG00000150394.
Subcellular location: Cell membrane
Subcellular location (Human Protein Atlas): Plasma membrane
Pathways (Reactome):
Cell-Cell communication: Adherens junctions interactions; CDH11 homotypic and heterotypic interactions
Gene Ontology:
Molecular function: beta-catenin binding; cadherin binding; calcium ion binding; identical protein binding
Biological process: adherens junction organization; calcium-dependent cell-cell adhesion; cell adhesion; cell migration; cell morphogenesis; cell-cell adhesion mediated by cadherin; cell-cell junction assembly; cell-cell adhesion; homophilic cell-cell adhesion; regulation of synapse organization
Cellular component: adherens junction; axon terminus; catenin complex; plasma membrane; synaptic cleft; glutamatergic synapse; membrane; synaptic membrane
Genetic constraint (gnomAD): Loss-of-function variants: 16 observed, 65.82 expected, observed/expected ratio (o/e) 0.24, 90% interval 0.16 to 0.37. The upper end of that interval is the gene's LOEUF score, 0.37, which puts it in group 1 of 6, group 1 being the genes least tolerant of losing a copy. Missense variants: 703 observed, 978.11 expected, observed/expected ratio (o/e) 0.72, 90% interval 0.68 to 0.76. Synonymous variants: 349 observed, 359.26 expected, observed/expected ratio (o/e) 0.97, 90% interval 0.89 to 1.06.
Homologues: Orthologues: pig CDH8 (99% identical), guinea pig CDH8 (98% identical), mouse Cdh8 (97% identical), macaque CDH8 (93% identical), rabbit CDH8 (88% identical), chimpanzee CDH8 (88% identical), rat Cdh8 (88% identical), tropical clawed frog cdh8 (85% identical). Paralogues in human: CDH11 (66% identical), CDH7 (58% identical), CDH10 (56% identical), CDH6 (56% identical), CDH20 (56% identical), CDH18 (55% identical), CDH12 (54% identical), CDH9 (54% identical), CDH24 (52% identical), CDH22 (49% identical), CDH19 (44% identical), CDH5 (38% identical), and 21 more.
Diseases named in the same sentence as CDH8 in open-access papers:
CDH8 is named in the same sentence as 35 diseases in open-access papers, as found by Europe PMC text mining. Sharing a sentence is not in itself a finding about the gene and the disease. The quoted sentences say what the papers report.
autism (16 papers, 2011 to 2025). Persistent deficits in social interaction and communication and interaction as well as a markedly restricted repertoire of activity and interest as well as repetitive patterns of behavior. "Cadherin-8 (encoded by Cdh8) is an integral membrane protein crucial for calcium-dependent intercellular adhesion and has recently been implicated in autism:." (PMID 40342964, 2025). "For example, results from our linear model implicated CDH8, a gene which encodes cadherin 8 (a protein which mediates calcium-dependent cell-cell adhesion, is expressed in brain and has been associated with autism and cortico-striatal circuits)." (PMID 39333502, 2024). "CDH8 haploinsufficiency is an autism and intellectual disability susceptibility factor, playing a key role in cerebellar development." (PMID 39654053, 2024). "More research on CDH8 has shown that mutations in the CDH8 gene lead to cerebellar hypoplasia and motor dysfunction, also an essential factor in autism." (PMID 38200892, 2024). "Multiple genes have been implicated in autism, including the cadherin superfamily of adhesion molecules, cadherin-8 and cadherin-11." (PMID 34135003, 2021). "Impaired neuronal connectivity has been suggested to represent a risk factor contributing to etiology of autism, which prompted us to investigate the involvement of cadherin-8 and cadherin-11 in autism." (PMID 34135003, 2021). "In this study, we first evaluated the potential roles of the autism candidate risk genes CDH8 and CDH11 by systematically investigating their expression and localization in mouse tissue." (PMID 34135003, 2021). "Previously, CDH8 has been found enriched in glutamatergic synapses of cortical neurons in mice and polymorphisms in the CDH8 gene has been implicated in autism." (PMID 33653397, 2021). "An example of a potential connection is described here between cadherin-8 and neuroligin-1, another autism risk candidate molecule." (PMID 34135003, 2021). "We found that CBP/p300 regulated genes were overlapped with the targets of CDH8-caused autism, including cell cycle and cytoskeleton and cell adhesion genes and ribonucleprotein complex genes." (PMID 32562237, 2020). "For instance, it has recently been described that mutations in CDH8 result in a specific subtype of autism in combination with gastrointestinal problems." (PMID 28274275, 2017). "Later, a study using the PPL statistical framework identified that CDH8 is expressed in the developing human cortex of ASDs family, which implicates CDH8 in susceptibility to autism." (PMID 25309321, 2014). "Mutations in Cdh8 and Plcb1 are associated with susceptibility to autism and the development of early-onset epilepsy, respectively." (PMID 22103416, 2011). "Our study not only describes a detailed characterization of the autism-risk genes CDH8 and CDH11, but also provides insights into novel functions of cadherin-11 in neural circuit development that may potentially be implicated in the etiology of autism." (PMID 34135003, 2021). "In contrast, NPCs from autistic individuals showed upregulation of CDH8, which may be at odds with the autism-associated loss-of-function mutations in the CDH8 gene." (PMID 34135003, 2021). "Cdh8 merited further study as it has recently been implicated in the susceptibility to autism and learning difficulties, disorders that may be attributed to defects in interneuron development." (PMID 30315415, 2019). "On the one hand, CDH8 is a negative regulator of autism, and CDH8 involves in the classical Wnt signaling pathway by directly binding to β-catenin or being recruited to the promoter regions of β-catenin-responsive genes." (PMID 36768153, 2023). "Induced pluripotent stem cell (iPSC)-derived cortical neural precursor cells (NPCs) and cortical organoids generated from individuals with autism showed upregulated CDH8 expression levels, but downregulated CDH11." (PMID 34135003, 2021).
autism (continued). "Together, these results show that both cadherin-8 and cadherin-11 levels are altered in cells derived from individuals with autism that mimic early stages of neural circuit development." (PMID 34135003, 2021). "The classical Type II cadherins cadherin-8 (Cdh8, CDH8) and cadherin-11 (Cdh11, CDH11) have been implicated as autism risk gene candidates." (PMID 34135003, 2021). "The variants in the CDH8 and CDH11 genes identified in individuals with autism are predicted to cause loss of function." (PMID 34135003, 2021). "We focused our study on the classical Type II cadherins cadherin-8 (Cdh8, CDH8) and cadherin-11 (Cdh11, CDH11) as these specific cadherins have been identified as autism risk genes in a genome-wide association study and by whole exome sequencing." (PMID 34135003, 2021). "A recent knockdown study implicated Cdh8 in the regulation and generation of normal cortical projections, neuronal morphology and cortico-striatal synapses, which are features affected in autism patients, suggesting that Cdh8 may play a role in corticogenesis and in the development of the disorder." (PMID 30315415, 2019). "Cadherin 8 (CDH8), which presents in the developing human cortex, is reported as an autism susceptibility gene in other recent research." (PMID 24756565, 2014). "In addition, other studies have identified rare mutations and SNP variants in CDH8 and CDH11 genes, respectively, in individuals with autism." (PMID 34135003, 2021). "CDH8 and CDH11 have been identified as autism-risk candidate genes." (PMID 34135003, 2021). "In fact, none of the individuals with autism tested in this study harbor damaging mutations in the CDH8 or CDH11 genes." (PMID 34135003, 2021). "The levels of cadherin-8 and cadherin-11 in human induced pluripotent stem cell (iPSC)-derived cortical neural precursor cells and cortical organoids of autistic individuals are both altered, strengthening that these two cadherins may be involved in autism etiology." (PMID 34135003, 2021). "However, the role of Cdh8 in interneuron development and potential contribution to autism has not been assessed." (PMID 30315415, 2019). "The autism cases investigated in this study did not carry any genetic alterations in CDH8 and CDH11 genes, and yet, they exhibited changes in protein levels of these two cadherins, further strengthening the hypothesis that cadherin signaling may represent an important pathway affected in autism." (PMID 34135003, 2021).
autism spectrum disorder (4 papers, 2012 to 2025). A spectrum of developmental disorders that includes autism, and Asperger syndrome. "CDH8 (language‐associated in males) encodes a crucial protein for the assembly of corticostriatal synapses and circuits and is a known risk gene for autism spectrum disorder." (PMID 40042063, 2025). "Disease enrichment analysis revealed that these genes are enriched in autism spectrum disorders in patients with ARID1B mutations, while there is a more general enrichment in intellectual disability in patients with SUV420H1 and CDH8 mutations." (PMID 40270680, 2025). "Microdeletion and microduplication copy number variations are found in patients with autism spectrum disorder and in a number of cases they include genes that are involved in the canonical Wnt signaling pathway (for example, FZD9, BCL9 or CDH8)." (PMID 23083465, 2012).
Intellectual disability (3 papers, 2023 to 2025). "It is noteworthy that RAB11B and RAB11B-AS1 are downregulated by CDH8, and therefore, known CDH8 variants may modulate the cellular level of RAB11B, leading to macrocephaly and intellectual disability." (PMID 37408531, 2023).
breast carcinoma (2 papers, 2021). "CDH8 codes for an integral membrane protein from the cadherin family where loss of CDH8 has been reported in breast carcinoma." (PMID 34922619, 2021).
cervical cancer (2 papers, 2013 to 2016). A primary or metastatic malignant neoplasm involving the cervix. "Promoter hypermethylation of ADCY8, CDH8, and ZNF582 was corroborated in five cervical cancer cell lines with two exceptions." (PMID 27651839, 2016). "Promoter methylation of ADCY8, CDH8, and ZNF582 was markedly elevated across all four stages of cervical carcinoma." (PMID 27651839, 2016). "Among the 49 PRC2 targets (defined by consistent hyper-MVPs) identified here were 10 genes of the cadherin superfamily in HPV+ HNSCC, including CDH8 and CDH13 (both also hypermethylated in cervical cancer, CDH18, CDH19, CDH23, PCDH10, PCDH15, PCDHB1, PCDHB4, and PCDHB15." (PMID 23419152, 2013). "TCGA data for the cervical cancer cohort (N = 231) revealed distinct hypermethylation patterns among ADCY8, ZNF582, and CDH8 for reported and non-reported clinical stages (median β value range, 0.427–0.632)." (PMID 27651839, 2016).
depression (2 papers, 2021). "As Cdh8, Cdh13, and Dcc/Netrin-1 have been linked to ASD, depression, and schizophrenia, investigating their role in wiring the healthy brain can provide important clues about how mPFC circuitry is perturbed in disease." (PMID 33949949, 2021).
aneurysmal diseases (1 paper, 2021). "However, the functions and mechanisms of both CDH8 and CDH11 in aneurysmal diseases have not been clarified." (PMID 33531038, 2021).
deafness (1 paper, 2018). An inherited or acquired condition characterized by the complete loss of the ability to hear from one or both ears. "The nonsense mutation (p.R920X) associated with nonsyndromic deafness is located in the Cadherin 8 of Extracellular (EC) domain." (PMID 29568747, 2018).
gastric cancer (1 paper, 2019). A primary or metastatic malignant neoplasm involving the stomach. "This latter finding is in accordance with recent studies which demonstrated that knocking down CDH8 expression in gastric cancer cell lines, MKN45 and NUGC4, promoted proliferation." (PMID 30315415, 2019).
head and neck cancer (1 paper, 2020). A primary or metastatic malignant neoplasm affecting the head and neck. "Second, CDH8 promoter hypermethylation has been documented in four head and neck cancer studies." (PMID 33178175, 2020).
kidney failure (1 paper, 2019). An acute or chronic condition that is characterized by the inability of the kidneys to adequately filter the blood. "The SNV rs10906850 nearby NMT2 was significantly associated with ICD code for renal/kidney failure (p = 0.008) and rs11645800 nearby CDH8 was nominally associated with renal/kidney failure." (PMID 31178898, 2019).
non-small cell lung carcinoma (1 paper, 2019). A group of at least three distinct histological types of lung cancer, including non-small cell squamous cell carcinoma, adenocarcinoma, and large cell carcinoma. "Cdh8 has also been implicated in metastasis in non-small cell lung cancer." (PMID 30315415, 2019).
Obesity (1 paper, 2021). Accumulation of substantial excess body fat. "Cadherin 8 (Cdh8) also contains SNPs with a strong signature of selection (LFMM q-value < 0.001) and has been linked to obesity and metabolic traits through QTL mapping and differential expression analysis in mice." (PMID 33914747, 2021).
renal cell carcinoma (1 paper, 2010). "Inappropriate CDH8 expression has been linked to a subset of renal cell carcinomas." (PMID 20485525, 2010).
retinoblastoma (1 paper, 2016). A malignant tumor that originates in the nuclear layer of the retina. "However, this does not directly discriminate CDH1 and CDH8 as retinoblastoma suppressors, and these discrepancies signify the difficulty of pinpointing a single gene as driver." (PMID 27126562, 2016).
tuberculosis (1 paper, 2024). A chronic, recurrent infection caused by the bacterium Mycobacterium tuberculosis. "For example, an endemic wild boar population was divided into a Mycobacterium tuberculosis-infected group and an uninfected group, and genome-wide association analysis screened CDH8 as a candidate gene for host genetic susceptibility to tuberculosis caused by divergent bacteria." (PMID 38200892, 2024).
cancer (4 papers, 2005 to 2025). A tumor composed of atypical neoplastic, often pleomorphic cells that invade other tissues. "Published literature on promoter methylation of ADCY8, CDH8, and ZNF582 has expanded recently and hypermethylation of one or more of these loci have been found in cancers of the breast, oropharynx, esophagus, and anus." (PMID 33178175, 2020). "Two cancer-related genes (RBL2 and CDH8) are three times more frequently lost than gained." (PMID 16457699, 2005).
tumor (4 papers, 2010 to 2022). "Of these, 83 were heterozygous novel SNPS, 3 were homozygous in the tumor only, presumably due to LOH, and 3 in NKX6-2, CDH8, and NFRKB were heterozygous point mutations." (PMID 20485525, 2010). "Taken together, ADCY8, CDH8, and ZNF582 promoter methylation are promising predictive and prognostic biomarkers for multiple tumor types crossing geographic and racial boundaries that undeniably merits further validation." (PMID 33178175, 2020). "Promoter methylation of four candidate tumor suppressor genes (adenylate cyclase 8 (ADCY8), cadherin 8, type 2 (CDH8), MGMT, and zinc finger protein 582 (ZNF582)) out of 48 genes screened was quantified by bisulfite-pyrosequencing of genomic DNA." (PMID 27651839, 2016). "However, increased median methylation (~10×) of ADCY8, CDH8, and ZNF582, but not MGMT, was noted in the tumor cohort (N = 257) compared with the three normal samples." (PMID 27651839, 2016).
bacterial infections (1 paper, 2024). "CDH8 is a classic cadherin which has been studied in bacterial infectious diseases." (PMID 38200892, 2024).
CDH8 also shares sentences with these, for which no sentence is quoted: epilepsy (2 papers); schizophrenia (2); Alzheimer disease (1); bipolar disorder (1); cerebral malaria (1); Cognitive impairment (1); Cri-du-chat syndrome (1); dementia (1); infection (1); microcephaly (1); Myocardial fibrosis (1); neurodevelopmental disorder (1); Onset (1); Pap (1); psychiatric disorder (1); Rubinstein-Taybi syndrome (1).